Y_RNA (Y RNA )
Gene: Miscellaneous RNA gene on chromosome 9 (133,302,470 to 133,302,563, forward strand). Ensembl gene ENSG00000201843.
Homologues: Orthologues: chimpanzee Y_RNA (97% identical), guinea pig Y_RNA (85% identical), dog Y_RNA (77% identical). Paralogues in human: Y_RNA (84% identical), Y_RNA (83% identical), RNY3 (82% identical), Y_RNA (82% identical), RNY3P1 (81% identical), Y_RNA (81% identical), Y_RNA (80% identical), Y_RNA (79% identical), RNY3P16 (78% identical), RNY3P4 (78% identical), Y_RNA (78% identical), RNY3P14 (77% identical), and 89 more.